MIR6736 (microRNA 6736)
Synonyms: hsa-mir-6736
Gene: MicroRNA gene on chromosome 1 (145,850,587 to 145,850,645, reverse strand). Ensembl gene ENSG00000278549.
Homologues: Orthologues: chimpanzee MIR6736 (100% identical).